RBP7 (retinol binding protein 7)
Diseases named in the same sentence as RBP7 in open-access papers (continued):
Sharing a sentence is not in itself a finding about the gene and the disease.
breast carcinoma (continued). "Moreover, reduced RBP7 expression correlates with tamoxifen resistance in ERα-positive breast cancer, particularly in luminal A subtype patients." (PMID 41301068, 2025). "Notably, we demonstrate that RBP4 and RBP7 have particularly important clinical relevance in breast cancer." (PMID 41301068, 2025). "In contrast, RBP7 has been more extensively studied in the context of breast cancer." (PMID 41301068, 2025). "The expression of RBP7 in normal breast tissues was higher than that in HR + breast cancer tissues." (PMID 38553715, 2024). "Increasing evidence proves that RBP7 plays a significant role in breast cancer (BC)." (PMID 38553715, 2024). "Therefore, we further analyzed the correlation between RBP7 and PIK3R3 in breast cancer and found that the expression levels of RBP7 and PIK3R3 were negatively correlated (R = −0.231, p = 6.79e − 15)." (PMID 36276273, 2022). "Notably, in breast cancer tissues, RBP7 is mainly expressed in epithelial cells with nuclear localization." (PMID 36276273, 2022). "In summary, our results demonstrate that the promoter methylation of RBP7 be related to its transcriptional silencing, which may be a reasonable explanation for the gene downregulation of RBP7 in breast cancer." (PMID 36276273, 2022). "Functional enrichment analysis demonstrated that downregulation of RBP7 expression may exert its biological influence on breast cancer through the PPAR pathway and the PI3K/AKT pathway." (PMID 36276273, 2022). "Our findings were consistent with other studies on the role of RBP7 in breast cancer." (PMID 36276273, 2022). "The results showed that RBP7 methylation mainly occurred in primary breast cancer, and the mRNA expression of RBP7 corresponding to hypermethylated samples is low, indicating a potential correlation between mRNA expression and DNA methylation of RBP7." (PMID 36276273, 2022). "Importantly, we found that both the mRNA and protein expression levels of RBP7 in breast cancer tissues were significantly lower than those in normal tissues." (PMID 36276273, 2022). "Then, we utilized the CPTAC database to analyze the protein expression of RBP7 in breast cancer and found that the protein expression of RBP7 in breast cancer was lower than that in normal tissues, which was consistent with the result of RBP7 expression in the TCGA database." (PMID 36276273, 2022). "RBP7 is positively regulated by E2 in breast cancer cells and mouse mammary gland." (PMID 30165855, 2018). "Reduced expression of RBP7 might lead to resistance to tamoxifen in luminal A breast cancer." (PMID 38553715, 2024). "Thus, we further explored the mechanism of RBP7 downregulation in breast cancer." (PMID 36276273, 2022). "Furthermore, we found that RBP7 has prognostic value for ER+ breast cancer." (PMID 36276273, 2022). "Furthermore, we used FROGgeneV2 to confirm the effect of RBP7 on the OS of breast cancer patients." (PMID 36276273, 2022). "In breast cancer, methylation-mediated silencing of RBP7 activates PPAR and PI3K/AKT signaling, whereas ectopic RBP7 expression suppresses AKT/SREBP1 activity and reduces fatty-acid accumulation in hormone receptor-positive cells." (PMID 41301068, 2025). "The staining patterns of RBP7 in adjacent non-cancerous tissue and breast cancer tissue also indicated a significant reduction in RBP7 expression levels within the tumor tissue." (PMID 41301068, 2025). "However, the prognostic value of RBP7, a new member of the CRBP family, in breast cancer is still unclear." (PMID 36276273, 2022). "RBP7, another member of the CRBP family, may also engage in crosstalk with RAR; thus, it may play an important role in mechanism regulation via RAR/ER in breast cancer." (PMID 36276273, 2022).
breast carcinoma (continued). "With the concept that low expression of RBP7 leads to poor prognosis of ER+ breast cancer patients, we further performed KEGG pathway analysis in ER+ breast cancer and found that RBP7 exerts its biological function through crosstalk with the PPAR and PI3K/AKT signalling pathways." (PMID 36276273, 2022). "In addition, we also validated the expression profiles of RBP7 across tumor and normal tissues of breast cancer using the online tool GENT2, and validated the prognostic impact of RBP7 on breast cancer using the online tool “Kaplan–Meier Plotter-Breast cancer”." (PMID 41301068, 2025). "Finally, we screened RBP7-targeting drugs from computational analysis of resistance (CARE) databases, which may provide new ideas for the treatment of breast cancer." (PMID 36276273, 2022). "However, the potential role of RBP7 in breast cancer has not yet been verified, and the mechanism remains unknown." (PMID 38553715, 2024). "However, as a novel member of the CRBP family, the clinical and prognostic significance of RBP7 in breast cancer is still unknown, and its functional role in breast cancer has never been documented." (PMID 36276273, 2022).
Obesity (3 papers, 2007 to 2026). Accumulation of substantial excess body fat. "The specific expression pattern of Rbp7 in adipose tissues combined with its effects on lipid accumulation suggests that RBP7 is a promising candidate for development of anti-obesity therapies." (PMID 35493071, 2022). "Our data indicate critical RBP7 functions in adipocytes: regulation of transcriptional activity of RARE and adipocytes differentiation, potentially providing a new target for obesity therapy." (PMID 35493071, 2022).
hepatocellular carcinoma (2 papers, 2025). A malignant tumor that arises from hepatocytes. "The association of UBE2C with RBP7, alongside other upregulated genes such as TK1 and TYMS, underscores its potential role in hepatocellular carcinoma progression and highlights UBE2C as a critical target for therapeutic intervention in this context." (PMID 41301068, 2025).
Hypertension (2 papers, 2015 to 2024). The presence of chronic increased pressure in the systemic arterial system. "RBP7 is a PPARγ (peroxisome proliferator-activated receptor γ) target gene and forms a positive feedback loop with PPARγ in hypertensive diseases." (PMID 38553715, 2024). "RBP7 plays important roles in hypertension, adipogenesis, cold exposure and nutritional treatment." (PMID 38553715, 2024).
ovarian carcinoma (2 papers, 2007 to 2022). A malignant neoplasm originating from the surface ovarian epithelium. "RBP7 is epigenetically silenced by DNA methylation in the promoter region in a high frequency of nasopharyngeal carcinomas as well as in some cancer cell lines (colon, prostatic and ovarian cancer)." (PMID 17940511, 2007).
acute respiratory distress syndrome (1 paper, 2025). Progressive and life-threatening pulmonary distress in the absence of an underlying pulmonary condition, usually following major trauma or surgery. "In a study on acute respiratory distress syndrome (ARDS), RBP7 was found to be closely associated with CD14 cells, and the high expression of TYMS in both CD14 and B cells suggests a synergistic relationship in regulating immune responses in ARDS." (PMID 41301068, 2025).
breast invasive carcinoma (1 paper, 2022). "Additionally, the results revealed that RBP7 mRNA expression levels were significantly lower in most cancer samples than their corresponding normal samples, including breast invasive carcinoma (BRCA), uterine corpus endometrial carcinoma (UCEC), and lung adenocarcinoma (LUAD)." (PMID 36276273, 2022).
colorectal cancer (1 paper, 2022). A primary or metastatic malignant neoplasm that affects the colon or rectum. "study results, we preliminarily understood the distribution of RBP7 in colorectal cancer." (PMID 35784334, 2022). "Clinical feature of colorectal cancer patients of RBP7 expression (TCGA cohorts)." (PMID 35784334, 2022).
colorectal tumor (1 paper, 2022). "At this stage, we have two hypotheses: one is that RBP7 might have a dual role in tumor and the other is that RBP7 may be genetically altered when expressed in colorectal tumor tissue." (PMID 35784334, 2022).
diabetic cardiomyopathy (1 paper, 2025). Diabetic cardiomyopathy is a disorder of the heart muscle in people with diabetes. "Rbp7 is also a member of the fatty acid binding protein family, which can promote fat production and participate in the expression of genes related to retinol metabolism, and the disorder of retinol metabolism also promotes the development of diabetic cardiomyopathy." (PMID 40296165, 2025).
endothelial dysfunction (1 paper, 2015). In vascular diseases, endothelial dysfunction is a systemic pathological state of the endothelium (the inner lining of blood vessels) and can be broadly defined as an imbalance between vasodilating and vasoconstricting substances produced by (or acting on) the endothelium. "Hu and his colleagues reported that RBP7 might normally mediate protective effects of PPARγ and that deletion of RBP7 might augment Ang II-induced endothelial dysfunction in mice, implying RBP7 was involved in BP regulation." (PMID 26517713, 2015).
gastric cancer (1 paper, 2022). A primary or metastatic malignant neoplasm involving the stomach. "The results of immunohistochemistry showed that the protein expression levels of RBP7, DES, SPP1, VIP, and PRKCG in gastric cancer tissues were higher than those in normal tissues, while PNOC, TNFRSF12A, and TUBB3 proteins are less expressed in gastric cancer tissues than normal tissues." (PMID 35174205, 2022).
glaucoma (1 paper, 2021). Increased pressure in the eyeball due to obstruction of the outflow of aqueous humor. "RBP7 which is located on the glaucoma locus GLC3B was uniquely upregulated in WTβ3 cells (Log2 FC = 1.925)." (PMID 34440692, 2021).
myocardial infarction (1 paper, 2023). Gross necrosis of the myocardium, as a result of interruption of the blood supply to the area, as in coronary thrombosis. "Some are anti-atherosclerotic, such as Cxcl12, which plays a protective role after myocardial infarction, and Rbp7, which helps to increase nitric oxide bioavailability." (PMID 36910156, 2023).
pulmonary fibrosis (1 paper, 2018). Chronic progressive interstitial lung disorder characterized by the replacement of the lung tissue by connective tissue, leading to progressive dyspnea, respiratory failure, or right heart failure. "We also report that E2 specifically down-regulated the expression of CLIC3 and RBP7 which have been associated with pathogenic mechanisms of pulmonary fibrosis." (PMID 30165855, 2018).
triple-negative breast carcinoma (1 paper, 2025). An invasive breast carcinoma which is negative for expression of estrogen receptor (ER), progesterone receptor (PR), and human epidermal growth factor receptor 2 (HER2). "We studied these proteins, especially RBP4 and RBP7, to learn how their levels differ across cancers and what that means for patients, with special attention to triple-negative breast cancer, a difficult-to-treat subtype." (PMID 41301068, 2025). "Our comprehensive analysis, using bioinformatics tools and experimental validations, revealed distinct expression profiles of RBP family members across various cancers, highlighting the critical role of RBP4 and RBP7 in the context of triple-negative breast cancer biology." (PMID 41301068, 2025). "Additionally, single-cell RNA sequencing (scRNA-seq) was used to analyze the expression of RBP4 and RBP7 in triple-negative breast cancer (TNBC), revealing their distribution across various cell types within the tumor microenvironment." (PMID 41301068, 2025).
uveal melanoma (1 paper, 2025). A melanoma derived from melanocytes of the uveal tract. "RBP7 plays a protective role in BRCA, KIRC, and uveal melanoma, but is a high-risk prognostic factor in COAD, and STAD." (PMID 41301068, 2025).
cancer (10 papers, 2007 to 2025). A tumor composed of atypical neoplastic, often pleomorphic cells that invade other tissues. "Among the 26 immune genes, RBP7 has been proved to be highly expressed as an independent biomarker of poor cancer-specific survival in early and advanced CC and is associated with CC progression." (PMID 34124251, 2021). "In addition, we conducted co-expression analysis using the TCGA database to reveal the association of RBP4 and RBP7 with immune checkpoints in pan-cancer." (PMID 41301068, 2025). "Loss of RBP7 impairs this regulatory circuit, resulting in oxidative stress and dysfunction in endothelial cells.Cancer cells have to endure oxidative stress throughout tumorigenesis, including during initiation, matrix detachment, transmission in the circulation, and relapse after therapy." (PMID 36276273, 2022). "Moreover, a significant increase in RBP7 expression has been observed in renal cell carcinomas and thus suggested that it may be associated with the development of certain types of cancer." (PMID 31598160, 2019). "Analysis of TCGA data revealed that RBP7 undergoes frequent genomic alterations across multiple cancer types, with amplification occurring in 0.54% and deletion in 1.34% of HCC cases." (PMID 40636697, 2025). "Further analysis of single-cell transcriptome data revealed the expression profiles of RBP4 and RBP7 in cancers." (PMID 41301068, 2025). "Using ROC curve analysis and Youden's index for cancer specific survival, we identified an optimal cut‐off H-score of 32.5 for dichotomal classification into cases with high or low RBP7 expression, respectively." (PMID 31598160, 2019). "Dysregulation of RBP7 expression in certain cancers hints at its potential influence on tumor biology, yet comprehensive studies are required to uncover its specific functions and therapeutic relevance in cancer contexts." (PMID 41301068, 2025). "Emerging evidence suggests that RBP7 may be involved in cancer development and progression, though its exact mechanisms remain under investigation." (PMID 41301068, 2025). "Thus, impairment of the regulatory circuit between RBP7 and PPARγ increases the opportunity to promote the occurrence of cancer." (PMID 36276273, 2022). "The mRNA expression levels of RBP7 were explored by TIMER in many cancer types." (PMID 36276273, 2022). "Indeed, Kaplan-Meier analysis and log-rank testing demonstrated significantly poorer cancer specific survival of patients whose tumors were RBP7 high when compared to RBP7 low cases (P = 0.003)." (PMID 31598160, 2019). "Also in this data set, Kaplan-Meier analysis and log-rank testing demonstrated a strong positive correlation of high RBP7 expression and poor cancer specific survival when compared to tumors with low RBP7 levels (P = 0.00007)." (PMID 31598160, 2019). "For example, androgen withdrawal-induced marked downregulation of relaxin, VEGF, vimentin and BMP-6, involved in cancer progression as well as upregulation of cellular retinol binding protein 7 and interferon-γ receptor, negatively regulating cancer progression, in LNCaP/IL-6#1." (PMID 19844233, 2009). "Interestingly, within individual cancers RBP7 expression was not evenly distributed but instead labelled tumor cell subsets, which was most apparent in cases with weak to moderate expression." (PMID 31598160, 2019).
tumor (10 papers, 2007 to 2025). "The tumor suppressor RBP7 (Retinol-Binding Protein 7) is linked to lipid metabolism and the PI3K–AKT pathway." (PMID 40427160, 2025). "Reduced RBP7 expression was associated with tumor progression and poor prognosis." (PMID 38553715, 2024). "Moreover, in our work, we found that RBP7 is a high-risk factor for GC, so figuring out how RBP7 drives these malignant features and how it affects the transcriptome of gastrointestinal tumor cells is our next research direction." (PMID 35174205, 2022). "In tumor cells, we analyzed the expression levels of the top 50 genes that were negatively and positively correlated with RBP7 expression." (PMID 41301068, 2025). "We employed survival analysis using the Kaplan–Meier method and utilized single-cell RNA sequencing (scRNA-seq) to investigate the roles of RBP4 and RBP7 in the tumor microenvironment." (PMID 41301068, 2025). "While RBP7 was primarily expressed in endothelial cells, it was also expressed at low levels in tumor epithelial cells, proliferating tumor cells, and luminal epithelial cells." (PMID 41301068, 2025). "Knockdown of RBP7 inhibited cell proliferation in vitro and suppressed tumor growth in vivo by inducing cell cycle arrest and apoptosis." (PMID 40636697, 2025). "Functional assays, including CCK8, colony formation, flow cytometry (FACS) analysis, Annexin V/7-AAD staining and xenograft tumor assay, were performed to determine the vitro and in vivo role of RBP7." (PMID 40636697, 2025). "Our finding showed that RBP7 is frequently enhanced in HCC tumor tissues, and its expression is closely correlated with patient prognosis across different HCC subtypes." (PMID 40636697, 2025). "In this study, we analyzed the TCGA and GTEx databases and found that normal tissues or para-tumor tissues tended to have relatively high levels of RBP7 expression compared with HR + BC tissues." (PMID 38553715, 2024). "The xenograft tumor mouse models suggested that overexpression of RBP7 resulted in a substantial decrease in tumor size." (PMID 38553715, 2024). "RBP7, as a tumor immune microenvironment (TIME) related gene, was found to have the potential of predicting chemotherapy resistance and poor prognosis of CRC patients." (PMID 35784334, 2022). "We found that RBP7 was lower expressed in tumor tissue than in normal but higher expressed in 5-FU resistant tumor tissues than in 5-FU sensitive tissues." (PMID 35784334, 2022). "The number of RBP7 positive tumor cells and expression intensities varied greatly, ranging from barely detectably in few, to strong expression in most tumor cells." (PMID 31598160, 2019). "Next, in order to assess RBP7 expression objectively, we applied a digital quantitative scoring approach to determine H-scores 16 that integrated the frequency (range 0 % - 100 %) and staining intensity (range 0 - 3) of RBP7 positive tumor cells for each case." (PMID 31598160, 2019). "We then analyzed different regions within each tumor, and observed that tumor cells close to the tumor edge showed significantly higher RBP7 expression scores when compared to tumor cells that were located in the tumor center." (PMID 31598160, 2019). "Consistent with the in vitro results, RBP7 KD substantially inhibited tumor growth." (PMID 40636697, 2025). "RBP7 is frequently elevated in HCC tumor tissues, particularly in early-stage patients." (PMID 40636697, 2025). "Together with evidence that SREBP1-driven lipid metabolic reprogramming fuels TNBC growth, angiogenesis, and immune escape, these observations support a model in which endothelial and luminal RBP7 constitute a protective lipid-regulatory hub at the tumor–vascular interface." (PMID 41301068, 2025). "RBP7 may function as a tumor suppressor in HR + BC by inhibiting the AKT/SREBP1 pathway and reducing fatty acid." (PMID 38553715, 2024).